RNF157 (ring finger protein 157)
Description:
E3 ubiquitin ligase that ubiquitinates APBB1 for its degradation by the proteasome and thus prevents apoptosis and promotes survival of neurons. Has a dual role in neurons as it is also required for dendrite growth and maintenance for which its ligase activity is not critical. May act as a scaffold molecule to regulate this process. Acts as a downstream effector of the interconnected PI3K and MAPK signaling pathways and thus participates in the regulation of the cell cycle.
Synonyms: KIAA1917
Tractability: PROTAC: its protein half-life has been measured.
Gene: Protein-coding gene on chromosome 17 (76,142,465 to 76,240,532, reverse strand). Ensembl gene ENSG00000141576.
Subcellular location: Cytoplasm
Subcellular location (Human Protein Atlas): Golgi apparatus; Vesicles
Gene Ontology:
Molecular function: ubiquitin protein ligase activity; ubiquitin-protein transferase activity
Biological process: negative regulation of apoptotic process; positive regulation of dendrite extension; protein ubiquitination
Cellular component: cell body; cytoplasm; cytoplasmic vesicle
Genetic constraint (gnomAD): Loss-of-function variants: 38 observed, 59.27 expected, observed/expected ratio (o/e) 0.64, 90% interval 0.49 to 0.84. The upper end of that interval is the gene's LOEUF score, 0.84, which puts it in group 3 of 6, group 1 being the genes least tolerant of losing a copy. Missense variants: 653 observed, 721.2 expected, observed/expected ratio (o/e) 0.91, 90% interval 0.85 to 0.97. Synonymous variants: 287 observed, 297.07 expected, observed/expected ratio (o/e) 0.97, 90% interval 0.88 to 1.07.
Homologues: Orthologues: chimpanzee RNF157 (98% identical), macaque RNF157 (98% identical), dog RNF157 (94% identical), guinea pig RNF157 (93% identical), mouse Rnf157 (93% identical), pig RNF157 (92% identical), rat Rnf157 (92% identical), rabbit RNF157 (87% identical), tropical clawed frog rnf157 (71% identical), zebrafish rnf157 (69% identical), Drosophila melanogaster Mrgn1 (38% identical), Caenorhabditis elegans mgrn-1 (27% identical). Paralogues in human: MGRN1 (46% identical).
Diseases named in the same sentence as RNF157 in open-access papers:
RNF157 is named in the same sentence as 15 diseases in open-access papers, as found by Europe PMC text mining. Sharing a sentence is not in itself a finding about the gene and the disease. The quoted sentences say what the papers report.
experimental autoimmune encephalomyelitis (2 papers, 2023 to 2025). An autoimmune demyelinating disease of the central nervous system that is produced experimentally in animals by the injection of homogenized brain or spinal cord in Freund's adjuvant. "RNF157 enhances Th1 cell differentiation and reduces Th17 cell differentiation by modulating HDAC1 ubiquitination, thus curbing experimental autoimmune encephalomyelitis." (PMID 40436857, 2025).
melanoma (2 papers, 2017 to 2023). A malignant, usually aggressive tumor composed of atypical, neoplastic melanocytes. "To gain a better understanding of the cellular role of RNF157, we undertook a proteomic approach to search for RNF157-interacting proteins in melanoma cells overexpressing FLAG-tagged GFP versus FLAG-tagged RNF157." (PMID 28655764, 2017). "In addition, we have shown that endogenous RNF157 knockdown increases apoptosis in combination with PI3K/MAPK pathway inhibition in melanoma cells." (PMID 28655764, 2017). "We first assessed RNF157 expression via immunoblotting during cell cycle progression and observed that RNF157 levels and molecular weight fluctuate in a cell cycle-dependent manner in both A2058 and 624MEL melanoma cells." (PMID 28655764, 2017). "The E3 ubiquitin ligase RNF157 showed substantial down-regulation of phosphorylation after MEK or PI3K inhibition and maximal blockade of phosphorylation after dual inhibition in both melanoma cell lines." (PMID 28655764, 2017). "Knockdown of endogenous RNF157 in melanoma cells leads to late S phase and G2/M arrest and induces apoptosis, the latter further potentiated by concurrent PI3K/MEK inhibition, consistent with a role for RNF157 in the cell cycle." (PMID 28655764, 2017). "Several proteins were pulled down specifically with immunoprecipitated RNF157-FLAG but not GFP-FLAG from two independent melanoma lines." (PMID 28655764, 2017).
prostate carcinoma (2 papers, 2022 to 2023). A carcinoma that arises from epithelial cells of the prostate gland. "A previous study showed that exosomal RNF157 mRNA from prostate cancer cells contributes to M2 macrophage polarization." (PMID 37441600, 2023).
autoimmune disorders (1 paper, 2023). "Overall, these results indicated that RNF157 may serve a critical role in autoimmunity through regulating the differentiation of CD4+ T cell subpopulations." (PMID 37441600, 2023).
epilepsy (1 paper, 2025). A brain disorder characterized by episodes of abnormally increased neuronal discharge resulting in transient episodes of sensory or motor neurological dysfunction, or psychic dysfunction. "We found that RP11-267M23.4, NBL1, ENTPD3-AS, RNF157, ZNF619, RPL14, and PARP1 showed causal relationship to epilepsy." (PMID 40624693, 2025). "Among all exposure genes, RP11-267M23.4, ENTPD3-AS, ZNF619, and RPL14 were demonstrated as risk factor to epilepsy, while NBL1, RNF157, and PARP1 were protective factors to epilepsy." (PMID 40624693, 2025). "In the MR analysis with epilepsy as the outcome, we identified seven positive results: RP11-267M23.4, NBL1, ENTPD3-AS1, RNF157, ZNF619, RPL14, and PARP1." (PMID 40624693, 2025).
lung carcinoma (1 paper, 2025). "Our functional experiments inhibiting these genes showed that loss of Ptgds, Arl2bp, Rnf157, and Syt11 can block lung cancer sphere formation." (PMID 40047406, 2025).
MARCH syndrome (1 paper, 2022). "Nevertheless, these theoretical analogies linking CEP55 with RNF157 require further experimentation, especially since the hydranencephaly of the MARCH syndrome is associated with a defect in the recruitment of CEP55 to the midbody." (PMID 36497121, 2022).
prostate adenocarcinoma (1 paper, 2022). "RNF157 expression was found to be aberrantly high in prostate adenocarcinoma (PRAD) tissues in comparison with normal tissues." (PMID 36263220, 2022).
tumor (6 papers, 2017 to 2026). "Based on single-cell analysis revealing RNF157's heterogeneous expression in cancer-associated fibroblasts (CAFs) and tumor-associated macrophages (TAMs), we performed validation experiments using lentiviral shRNAs targeting FAP in CAFs and CD11b in TAMs." (PMID 41657776, 2026). "The mRNA expression levels of STMN1, CLSPN, MDK, RNFT2, PRR11, and RNF157 were significantly increased in HCC tumor tissue; on the contrary, GHR was significantly decreased compared with normal tissues." (PMID 37542549, 2023). "Despite these limitations, we have demonstrated that knockdown of endogenous RNF157 leads to cell cycle arrest during the late S phase and G2/M checkpoint in tumor cells, supporting a role of RNF157 in promoting cell cycle progression." (PMID 28655764, 2017). "To test whether these genes regulate tumor cell growth we knocked down each of these genes (Ptgds, Arl2bp, Rnf157, and Syt11) in the KP cell line." (PMID 40047406, 2025). "Through in vivo study, we saw that RNF157 down-regulation in PC-3 cells could inhibit xenograft tumor growth, but PC-3-derived exosomes could abrogate the former suppressive impact." (PMID 36263220, 2022). "Moreover, IHC assay revealed that Ki67 expression in tumor tissues was reduced by RNF157 interference, but rescued after additional treatment of PC-3-secreted exosomes." (PMID 36263220, 2022). "RT-qPCR results confirmed that the down-regulated RNF157 expression in the tumor tissues obtained from PC-3/sh-RNF157-1 group could be rescued after additional injection of PC-3 exosomes." (PMID 36263220, 2022). "Moreover, our animal study revealed that RNF157 mRNA carried by exosomes could promote PCa tumor growth via promoting M2 polarization of macrophages." (PMID 36263220, 2022). "RNF157-mediated ubiquitination promotes DHX58 degradation, thereby accelerating tumor proliferation, whereas MATR3 enhances carcinogenesis by inhibiting DHX58-dependent IFN-I signaling." (PMID 41569991, 2026). "Exosome-mediated RNF157 mRNA from PCa cells results in M2 macrophage polarization via destabilizing HDAC1, consequently promoting PCa tumor progression." (PMID 36263220, 2022). "Our study reveals that RNF157, a novel E3 ubiquitin ligase, acts at the interface between the PI3K and MAPK pathways and the cell cycle machinery to promote cell cycle progression and tumor cell survival." (PMID 28655764, 2017).
cancer (5 papers, 2021 to 2026). A tumor composed of atypical neoplastic, often pleomorphic cells that invade other tissues. "RNF157, part of the E3 ubiquitin ligase family, is essential for protein degradation and has implications in neurodegenerative diseases and cancer." (PMID 40624693, 2025). "Finally, it is worth mentioning that genes involved in ubiquitination processes and linked to cancer were among the significantly correlated genes (BAP1, RNF157, UBQLN2)." (PMID 37730697, 2023).
RNF157 also shares sentences with these, for which no sentence is quoted: hepatocellular carcinoma (1 paper); Hyperglycemia (1); metabolic disorders (1); neurodegenerative disease (1); Obesity (1).